IL6R (interleukin 6 receptor)
Diseases named in the same sentence as IL6R in open-access papers (continued):
Sharing a sentence is not in itself a finding about the gene and the disease.
infection (continued). "Fourth, species specific differences in the use of cleavage events as has been reported for IL-6R draw an even more complex view of the ADAM protease web in infection." (PMID 33392273, 2020). "While GFP-negative bystander mDCs displayed 60–70% lower IL6R surface expression in the wt infection 16–24 hpi, Δvhs-infected mDCs express ~25% reduced IL6R levels, relative to the respective mock control." (PMID 32983130, 2020). "In contrast, HSV-1 wt-infected mDCs already exhibited a severe reduction of IL6R mRNA levels after 2 h of infection." (PMID 32983130, 2020). "We suggest that both these parameters should be considered relevant contributing factors for infection occurrence in patients on anti-IL-6R therapy." (PMID 31261772, 2019). "Comparisons of infection rates between anti-IL-6R and antitumor necrosis factor α (TNFα) therapy have also been conducted, with some observational cohort studies finding a higher infection rate in tocilizumab." (PMID 31261772, 2019). "During follow-up, a total of 29 infections were registered, 89.66% (n = 26) in the anti-IL-6R group and 10.34% (n = 3) in the anti-TNFα group." (PMID 31261772, 2019). "The beneficial impact of anti–IL-6R treatment was reduced at later time points of infection in both WT and Ifitm3–/– mice." (PMID 28240600, 2017). "Using co-immunoprecipitation assays, we observed a stable association between IL-6R, Lyn and Ezrin in mouse AMs after PAO1 infection." (PMID 29263906, 2016). "To investigate this, we infected control and iron supplemented pMacs with UPEC for 3 and 6 h; during both iron supplementation and infection, we treated the pMacs with either a control antibody or anti‐IL‐6Rα." (PMID 27980776, 2016). "At 32 weeks after infection, compared to control mice, anti-IL-6R Ab-treated mice had similar TB CFU counts in the lungs but higher counts in liver and spleen (data not shown)." (PMID 21603208, 2011). "The genes that were suggestive for association with PTB in fetal (IL1A, IL4 and MMP8) and maternal samples (IL-1R2 and IL-6R) in both the MoBa and Cenn studies were mainly infection and inflammation genes (sector D)." (PMID 20140262, 2010). "Additionally, both the IL-6Rα and GM-CSFRα showed enhanced expression during infection, further differing from IL-27Rα." (PMID 39868131, 2025). "The upregulation of IL13RA1, OSMR, CRLF2, and IL6R in our study may indicate responses to maintain neuromuscular integrity under infection-induced stress." (PMID 40943072, 2025). "This trend may be partly attributed to regular clinic visits, early detection, appropriate management of infections, and the discontinuation of IL-6R inhibitor therapy upon suspicion of infection." (PMID 39703501, 2024). "Overall, we observed an association between IL6R and a modest but significantly increased odds of serious infection in AFR but not EUR [AFR OR 1.03, 95% CI 1.01–1.04 vs EUR with OR 1.01, 95% CI 1.00–1.01]." (PMID 38580710, 2024). "Based on findings from the present study, we anticipate that in studies with adequately sized populations, we would anticipate higher WBC among individuals of AFR ancestry on IL6R blockade, as well as a potential small increased odds for serious infection compared to EUR." (PMID 38580710, 2024). "Our results suggest that targeting IL6R may be associated with higher WBC count and a potential modest signal for higher infection risk among individuals of AFR vs EUR descent." (PMID 38580710, 2024). "In our cohort, tocilizumab use was limited (one or two doses), therefore not conditioning the maintained blockage of IL-6R and avoiding the possible long-term immunosuppression and risk of infection." (PMID 34406633, 2022). "Monitoring neutrophil CD64 may also be helpful for the early detection of infection in the patients treated with interleukin-6 receptor antagonists." (PMID 33804790, 2021).
infection (continued). "In addition, this study suggested that the vhs protein plays a role in ILR6 expression in bystander mDCs, as the infection of mDCs with an HSV-1 virus that lacks this viral protein showed partial recovery of the expression levels of IL6R in bystander DCs." (PMID 34895058, 2021). "Mechanistically, IL6R downregulation in uninfected bystander DCs was associated with the transfer of HSV-1-derived noninfectious L-particles produced during infection of mDCs." (PMID 34895058, 2021). "The shorter terminal half-life of α-IL-6 mAb (T1/2 = 57h) versus α-IL-6R mAb (T1/2 = 223h), possibly due to isotype specific differences in glycosylation may help explain why giving α-IL-6 mAb early after infection provided the most observed clinical benefit." (PMID 33071786, 2020). "Supporting our hypothesis, this antibody interfered with the transmission of released L-particles from infected to uninfected bystander mDCs during our coculture infection experiments and inhibited IL6R modulation on these cells." (PMID 32983130, 2020). "Furthermore, the modulation of IL6R surface expression on bystander mDCs was less prominent upon HSV-1 Δvhs infection, compared to HSV-1 wt infection (blue line)." (PMID 32983130, 2020). "Three infections were considered serious, 1 in the anti-IL-6R group and 2 in the anti-TNFα group." (PMID 31261772, 2019). "Thus, during the acute phase of an infection when B cells differentiate to ASCs, when there is an abundance of free IL-6, ASCs signal through IL-6 through the cell surface IL-6 receptor (IL-6R)." (PMID 31572364, 2019). "We further examined whether a combination of anti-IL-6R and Xiap−/− Treg cells restored the resistance of Xiap−/− mice to infection-induced inflammation and lethality." (PMID 29386580, 2018). "Moreover, a combination of Xiap−/− Treg cells and anti-IL-6R corrects the vulnerability of Xiap−/− mice to infection." (PMID 29386580, 2018). "Control of infection depends on classical IL-6 signaling via membrane IL-6Rα, but IL-6 target cells and protective mechanisms remain unclear." (PMID 30169526, 2018). "Our genetic experiment did not include infection as an outcome and published evidence for the IL6R rs7529229 variant was scarce." (PMID 22421340, 2012). "The increased growth of TB in anti-IL-6R Ab-treated mice at later stages of infection may be due to decreased effector T cell activity." (PMID 21603208, 2011). "Furthermore, IL6R protein expression was up-regulated in the infection group." (PMID 36548652, 2022). "In addition, we performed IL6R mRNA expression analyses at early time points post infection." (PMID 32983130, 2020). "Collectively, this evidence suggests that unknown activities of live pathogen infection regulate myeloid differentiation involving an IL-6R-mediated process and implies cross-talking of regulatory pathways between live Mtb, IL-6 and IFN signaling to boost myeloid differentiation of CD34+ cells." (PMID 31637998, 2019). "Interleukin-6 (IL-6) is one of the cytokines involved in SARS-CoV-2-induced inflammatory response and monoclonal antibodies against the interleukin-6 receptor (IL-6R)—namely tocilizumab (TCZ) and sarilumab (SAR)—have been used in severe infection." (PMID 37218940, 2023). "By contrast, in patients with critical disease, the beneficial effect of anti-IL-6/IL-6R/JAK antibodies on mortality became indistinct, and resulted in an evident trend of increased secondary infection rates." (PMID 33384605, 2020). "In contrast, the IL6R expression levels on uninfected GFP-negative bystander mDCs were notably different among an HSV-1 wt and HSV-1 Δvhs infection (blue lines)." (PMID 32983130, 2020). "Infection of HepG2 cells and PHH by HCMV resulted in the production of IL-6 and the subsequent activation of the IL-6R-JAK-STAT3 pathway." (PMID 23555719, 2013).
infection (continued). "In order to elucidate which viral protein contributes to IL6R regulation during HSV-1 infection, different HSV-1 strains lacking specific viral proteins were tested regarding their impact on IL6R modulation during mDC infection." (PMID 32983130, 2020). "Our results showed that up-regulation of STAT3 phosphorylation due to TLT2 overexpression following H37Rv infection was not blocked by pretreatment with anti-IL-6Rα." (PMID 33042115, 2020). "Our finding that IL6R expression is also affected on GFP-negative bystander mDCs, in the context of an infection using pure H-particles (MOI of 0.65), supports the hypothesis that L-particles are responsible for this IL6R regulation." (PMID 32983130, 2020). "A few genes were downregulated 4 h after infection: caspase 8 (Casp8), nuclear receptor subfamily 2, group C, member 2 (Nr2c2/TAK1), mitogen-activated protein kinase 9 (Mapk9/JNK2) and interleukin 6 receptor-alpha (Il6ra)." (PMID 30555476, 2018). "The presence of both Src homolog 2 (SH2) and SH3 domains of Lyn was responsible for interacting with IL-6R upon PAO1 infection in MH-S cells, whereas the kinase domain was not." (PMID 29263906, 2016). "Interestingly, no reversal of the infection phenotype of the IL-6 transgenic parasites was observed upon IL-6R blockade." (PMID 37143657, 2023). "Xiap−/− iTreg cells were administered 2 days after infection, with or without by anti-IL-6R." (PMID 29386580, 2018). "In contrast, il6r subunit knockdown did not impair the infection-driven granulopoietic response." (PMID 29883484, 2018). "Importantly, the IL-6Rα+IL-7R+ DP population increased with time post infection, whereas effector TFH and non-TFH (IL-7RLO) populations decreased." (PMID 26743592, 2016). "We then determined whether IL‐6 signaling was required for pMacs to limit the ability of UPEC to exploit extra‐macrophagic free iron by treating pMacs in the presence or absence of iron supplementation during the infection course, with a control antibody or anti‐IL‐6Rα added during infection." (PMID 27980776, 2016). "Deletion of IL-6Rα in CD4+ and CD8+ T cells did not alter the control of L. monocytogenes since we observed similar bacterial titers in organs of Il6rafl/fl×CD4cre and control mice after primary and secondary infections." (PMID 30169526, 2018).
cardiovascular disease (32 papers, 2011 to 2024). "We found a causal relationship between the elevated level of soluble IL6R and a lower risk of cardiovascular disease (P = 2.35 × 10–24, Benjamini–Hochberg FDR = 1.08 × 10–22)." (PMID 38565889, 2024). "Individuals carrying the IL6R polymorphism rs2228145 show enhanced sIL‐6R and IL‐6 levels, reduced C‐reactive protein and a lower risk of cardiovascular disease." (PMID 34618359, 2022). "By leveraging whole-exome sequencing of individuals in the UK Biobank, CHIP carriers who also harbored the IL6R p.Asp358Ala mutation had significant attenuation of incident cardiovascular disease." (PMID 35122117, 2022). "Previous studies indicated that IL6R p.Asp358Ala [a commonly occurring variant in the IL-6 receptor (IL-6R) gene] could disrupt IL-6 signaling and provide a genetic proxy for tocilizumab, which reduces the risk of cardiovascular diseases in CHIP carriers." (PMID 38104193, 2023). "Indeed, it has been demonstrated that cardiac long-term IL-6 signalling or cardiac over production of IL-6R have a causal role in cardiovascular disease." (PMID 34071707, 2021). "In the further analysis on the association between VTE-associated proteins and cardiovascular comorbidities, genetically predicted levels of interleukin-6 receptor subunit alpha (IL-6 sRa) were inversely associated with VTE and 4 cardiovascular diseases." (PMID 38029854, 2024). "Among these associated protein-coding genes, MMP1, CTSB, POMC, RETN, and IL6R are known to be associated with SCAD or other cardiovascular diseases." (PMID 35425820, 2022). "It seems that the role of AAG in inflammatory progression needs to be further investigated, also in view of the recent data that demonstrated the importance of IL-6 and IL-6R (interleukin-6 receptor) in cardiovascular diseases." (PMID 34566895, 2021). "We also demonstrated confirmatory evidence for the causal role of four further proteins (FGF5, IL6R, LPL, LTA) in cardiovascular disease risk." (PMID 32628676, 2020). "IL-6 family play important roles in pathological process of cardiovascular diseases, and the IL6R-mediated JAK/STAT signaling pathway has been shown to participate in angiogenesis regulation and inflammation response." (PMID 30975181, 2019). "Specific SNPs in IL-6R lead to higher levels of sIL-6R and are also associated with higher baseline CRP and increased incidences of inflammatory and cardiovascular diseases." (PMID 27809289, 2016). "In the Guangzhou Biobank Cohort Study-Cardiovascular Disease (GBCS-CVD) sub-cohort study, the A allele of IL-6R rs8192284 A/C also was associated with increased TG levels among aged Chinese." (PMID 21835044, 2011). "In particular, the SNP rs2228145 (also known as Asp358Ala) in the gene IL6R has been identified as functional, with strong associations with biomarkers of IL-6 signaling (e.g., CRP, fibrinogen, plasma IL-6R levels) and with a number of traits, such as cardiovascular disease." (PMID 36801374, 2023). "Biomarker [8,] and human genetic results with similar strength to those of this study have formed part of the evidence basis for efforts to re-purpose IL-6R inhibitory therapy in cardiovascular disease (e.g. clinicaltrials.gov registered trials number NCT03004703, NCT01491074, or NCT02419937)." (PMID 33096487, 2020). "A recent study suggested that CHIP carriers with genetic deficiency of IL-6 signaling (by carrying IL6R p.Asp358Ala versus wild-type) had a greater reduction in cardiovascular disease risk when compared to non-CHIP carriers with genetic IL-6 signaling deficiency." (PMID 38104193, 2023). "However, the association between IL6R genotype and longevity has not been reported despite strong evidence for association of cardiovascular disease with IL-6 and sIL-6R phenotypes." (PMID 24381713, 2013).
inflammation (9 papers, 2011 to 2024). Aberrant reaction of the microcirculation characterized by movement of fluid and leukocytes from the blood into extravascular tissues. "Whereas Treg development during experimental airway inflammation is controlled via membrane-bound IL-6R, IL-6 trans-signaling orchestrates T cell recruitment in an experimental peritoneal inflammation model." (PMID 31694340, 2019). "In conclusion, our study demonstrates for the first time that leukocyte ADAM17 regulates acute lung inflammation by modulating intra-alveolar neutrophil levels and the shedding of IL-6R, L-selectin, and TNF-α." (PMID 21603616, 2011). "IL-6R expression was increased by 110% following lipid droplet accumulation, supporting a role of lipid droplet remodeling in overactive IL-6 trans-signaling-induced cardiac inflammation." (PMID 39063055, 2024). "Taken together, the results above suggest that ADAM17 is the primary sheddase of L-selectin and TNF-α by alveolar leukocytes, but not of the IL-6R during acute pulmonary inflammation." (PMID 21603616, 2011). "Our results reveal that in the context of lung inflammation, ADAM17 participates in the shedding of IL-6R, but in contrast to TNF-α and L-selectin, ADAM17 is not the primary sheddase of leukocyte IL-6R." (PMID 21603616, 2011).
bacterial infections (8 papers, 2016 to 2025). "Generally, the primary adverse effects of anti-IL-6/IL-6R antibodies are associated with bacterial infections." (PMID 39206193, 2024). "IL-6/IL-6R/JAK blockade therapeutics were reported to increase the risk of secondary bacterial infection." (PMID 33384605, 2020). "We for the first time demonstrate that during bacterial infection, a Lyn–IL-6R–Ezrin complex negatively regulates the IL-6/STAT3 signaling pathway in murine AMs." (PMID 29263906, 2016). "Interleukin 6 (IL-6), acting via the IL-6 receptor (IL6R) and signal transducer and activator of transcription-3 (STAT3), limits neutrophil recruitment once bacterial infections are resolved." (PMID 26813342, 2016).
psychiatric disorder (7 papers, 2012 to 2025). A disorder characterized by behavioral and/or psychological abnormalities, often accompanied by physical symptoms. "Increased levels of pro-inflammatory factors such as C-reactive protein and interleukin-6 receptor, which are associated with psychiatric disease, have been observed during European winters." (PMID 28962597, 2017). "Genotyping patients for IL6R rs2228145 while measuring their IL6 and CRP levels could be useful tools as non-specific diagnostic markers of alcohol- addicted patients with comorbid psychiatric disorders." (PMID 38275640, 2023).
infectious disease (5 papers, 2021 to 2024). A disorder directly resulting from the presence and activity of a microbial, viral, or parasitic agent in humans. "Several observational and randomized studies demonstrated that tocilizumab, an IL-6R blocker, improves survival in critically ill patients both in infectious disease and intensive care units." (PMID 37215114, 2023).
neurodegenerative disease (5 papers, 2020 to 2025). A disorder of the central nervous system characterized by gradual and progressive loss of neural tissue and neurologic function. "Patients with OSA have aberrantly low levels of four soluble cytokine receptors associated with neurodegenerative disease, gp130, IL6R, TNFR1, and TNFR2." (PMID 33037528, 2021). "These pathways were, in general, shared across all neurodegenerative diseases, even though the major overlap was found for the synaptic functions (BDNF, CCL2, ACHE, GFAP, NEFH or NEFL) and microglia pathways (TREM2, IL13, IL6R IFNG)." (PMID 41250190, 2025).
neurological diseases (5 papers, 2017 to 2024). "Tocilizumab, as a humanized IL-6 receptor (IL-6R) monoclonal antibody approved for the clinic, has been applied in the treatment of neurological diseases in recent years, but the treatment effect of Tocilizumab on the TJs restoration of the blood-spinal cord barrier (BSCB) after SCI remains unclear." (PMID 36624478, 2023).
respiratory disease (5 papers, 2017 to 2025). "Thus, a MR study was conducted to explore the potential effect of IL6R blockade on risk of respiratory diseases." (PMID 38898459, 2024). "This study uses Mendelian randomization to examine the effects of IL6R blockade on respiratory diseases." (PMID 38898459, 2024). "These insights suggest IL6R downregulation as a potential therapeutic target for respiratory diseases, meriting further clinical investigation." (PMID 38898459, 2024). "Targeting IL6R may serve as an actionable therapeutic target for mitigating specific respiratory disease risks and warrants further investigation in clinical trials." (PMID 38898459, 2024).
cardiac disease (4 papers, 2020 to 2024). "The majority of IL6R-phenotype associations within EUR subjects pertained to vascular and cardiac disease." (PMID 38580710, 2024).
adenocarcinoma (3 papers, 2019 to 2021). A common cancer characterized by the presence of malignant glandular cells. "In primary adenocarcinoma of the colon, IL-6R expression has been positively correlated with EMT-associated mesenchymal markers SNAIL, SLUG, VIM, ZEB1, and ZEB2." (PMID 31741710, 2019). "Interestingly, miR-155 expression was inversely correlated with IL6R and AXL, which were at the same time associated with the presence of EMT CTCs in adenocarcinoma." (PMID 31703465, 2019).
kidney disease (3 papers, 2018 to 2023). "Finally, no other relation was found amongst soluble IL-6R with the GLA mutation status, age, gender, FD specific (ERT or chaperonic) and other therapies, kidney disease biomarkers, and the levels of lyso-Gb3." (PMID 38202225, 2023).
metabolic disorders (2 papers, 2018 to 2020). "Expression of some of these genes (IL6R, WNK1, GRN) has been previously reported to correlate with metabolic disorders." (PMID 32956382, 2020). "The implication of altered IL-6/IL-6R signaling for arrhythmias in patients with metabolic disorders is currently not clear." (PMID 30666212, 2018).